HOMER1 (homer scaffold protein 1)
Diseases named in the same sentence as HOMER1 in open-access papers (continued):
Sharing a sentence is not in itself a finding about the gene and the disease.
breast carcinoma (4 papers, 2021 to 2025). "This discrepancy may be addressed by evaluating additional cell line models for both prostate and breast cancer to understand if unique genomic or epigenetic factors (e.g., loss of promoter methylation) drive HOMER1 expression and contribute to therapy resistance." (PMID 39578659, 2025). "To investigate the potential roles of HOMER genes in breast cancer, we first explored the expression patterns of HOMER1-3 in the Cancer Genome Atlas (TCGA) breast cancer datasets (BRCA)." (PMID 33407765, 2021). "High gene expression of TNFRSF9, HOMER1, and LRP1 were all significantly correlated with worse relapse free survival in breast cancer." (PMID 39483900, 2024). "Interestingly, bulk gene expression studies from tumors found that HOMER1 was prognostic of worse PFS in breast cancer but not in prostate cancer, whereas cell line data suggested the opposite." (PMID 39578659, 2025). "However, no reports of HOMER1’s involvement in breast cancer were found." (PMID 37987362, 2023).
psychosis (4 papers, 2017 to 2026). "Finally, Homer1 gene variants have been associated with neuropsychiatric disorders such as psychosis in Parkinson disease, major depression pathophysiology, and response to lithium treatment." (PMID 29321734, 2017).
amyloid (3 papers, 2020 to 2025). "As is the case of HOMER1, circRNA species of specific genes seem to be associated with amyloid deposits, which opens the path for studying these molecules as biomarkers of synaptopathies or even novel pharmacological targets for AD." (PMID 34502114, 2021).
brain injury (3 papers, 2015 to 2024). Acute and chronic (see also brain INJURIES, CHRONIC) injuries to the brain, including the cerebral hemispheres, CEREBELLUM, and brain STEM. "In contrast, blocking the formation of the mGluR1-Homer1 complex by downregulating Homer1 expression attenuates neuronal injury in a variety of excitotoxicity-associated neurological diseases, such as neurodegeneration and acute brain injury." (PMID 38531909, 2024). "Therefore, Homer1 conditional knockout mice (Homer1flox/flox/Nestin-Cre+/−) were constructed to investigate the protective role of Homer1 protein in ischemic brain injury." (PMID 38091015, 2024).
diabetes (3 papers, 2014 to 2022). "The results of multivariate logistic regression analysis showed that smoking, hypertension, diabetes, alcohol consumption, obesity, HDL-C, FGF23, SAH, Hcy, Homer1 were risk factors for coronary heart disease." (PMID 35546659, 2022). "It was suggested that CHD is closely related to smoking, hypertension, diabetes, alcohol consumption, obesity, HDL-C, FGF23, SAH, Hcy and HOMER1, and FGF23, SAH, Hcy and HOMER1 are new risk factors for CHD, which may have an important reference value for the clinical diagnosis of CHD." (PMID 35546659, 2022). "The gene expression of Homer1, Homer2, Homer3, IL-1β, and TNF-α were analyzed by hypertension and diabetes between CAD patients and controls." (PMID 25551602, 2014). "Subgroup analyses of the gene expression of Homer1, Homer2, Homer3, IL-1β, and TNF-α between CAD patients and controls by hypertension and diabetes." (PMID 25551602, 2014). "For Homer1, the gene expression differed significantly between CAD patients and controls in participants of hypertension (p < 0.001), normal blood pressure (p = 0.001), diabetes (p = 0.01), and normal glucose (p < 0.001)." (PMID 25551602, 2014).
Dyskinesia (3 papers, 2017 to 2025). A movement disorder which consists of effects including diminished voluntary movements and the presence of involuntary movements. "Variants in ADORA2A SNPs and HOMER1 have been linked to L-dopa -induced dyskinesia and psychotic symptoms." (PMID 39392484, 2025). "Lower risk of L-dopa-associated dyskinesias was found in patients with Homer protein homolog 1 (HOMER1) rs4704560 G allele polymorphism." (PMID 34281267, 2021). "rs474559 G allele (HOMER1) have lower prevalence of dyskinesia as it might disrupt the glutamatergic transmission." (PMID 28927418, 2017). "On the other hand, SNPs in the mTOR pathway genes, BDNF, HOMER1 and DAT have been implicated in either increased or reduced risk for dyskinesias, but with single studies that are yet to be corroborated in larger cohorts." (PMID 34281267, 2021). "With 13, 14 CAn STR repeats in DRD2 gene being the most significant variant associated with dyskinesia, followed by rs1801133 (MTHFR) associated with hyper-homocysteinemia, rs474559 (HOMER1) with hallucinations." (PMID 28927418, 2017). "For instance, among ADR studies, CAn STR 13, 14 (DRD2) was found to be most significantly associated with dyskinesia, rs1801133 (MTHFR) with hyper-homocysteinemia, and rs474559 (HOMER1) with hallucination." (PMID 28927418, 2017). "In American (AMR) population, Brazilians constituted four studies determining rs4704559 (HOMER1), rs2298383 (ADORA2A), rs1800497 (ANKK1) associated with dyskinesia, rs3761422 (ADORA2A) with motor fluctuation and rs28363170 (DAT1) with hallucination." (PMID 28927418, 2017). "From 37 candidate studies on levodopa toxicity, 18 genes were found associated, of which, CAn STR 13, 14 (DRD2) was most significantly associated with dyskinesia, followed by rs1801133 (MTHFR) with hyper-homocysteinemia, and rs474559 (HOMER1) with hallucination." (PMID 28927418, 2017).
glioma (3 papers, 2021 to 2026). A benign or malignant brain and spinal cord tumor that arises from glial cells (astrocytes, oligodendrocytes, ependymal cells). "In our hGliCS model potential neuron-glioma-synapses were observed by multiplexing with spectral separation on immunofluorescent stainings against the presynaptic marker SV2 and postsynaptic marker Homer1." (PMID 40188875, 2026). "This demonstrated an increased number of colocalization points and postsynaptic homer-1+ punctum size in glioma and neuronal processes in HFC–neuron co-cultures compared with LFC–neuron co-cultures, additionally indicating a role for HFC glioma cells in synaptogenesis." (PMID 37138086, 2023).
hepatocellular carcinoma (3 papers, 2019 to 2022). A malignant tumor that arises from hepatocytes. "Moreover, HOMER1 is a highly expressed protein in hepatocellular carcinoma tissues and is a key gene associated with glycolysis." (PMID 35642195, 2022). "We identified six mRNAs (DPYSL4, HOMER1, ABCB6, CENPA, CDK1, STMN1) significantly associated with overall survival in the Cox proportional regression model for hepatocellular carcinoma." (PMID 31790363, 2019). "However, the significance of HOMER1 and PHKA2 in glycolysis and in evaluating the prognosis of hepatocellular carcinoma patients remains unknown, and our current study suggested a possible role of them in glycolysis and HCC progression." (PMID 35924040, 2022).
intracerebral hemorrhage (3 papers, 2022 to 2024). A cerebrovascular disorder characterized by bleeding into one or both cerebral hemispheres including the basal ganglia and the cerebral cortex. "Homer scaffold protein 1 (Homer1), as a neuroprotective protein, was found to improve the functional recovery of intracerebral hemorrhage in mice by promoting the transformation of A1 astrocytes into A2 astrocytes." (PMID 37641874, 2024).
ischemia (3 papers, 2015 to 2024). A hypoperfusion of the BLOOD through an organ or tissue caused by a PATHOLOGIC CONSTRICTION or obstruction of its BLOOD VESSELS, or an absence of BLOOD CIRCULATION. "A possible reason was that when the body experiences ischemia, the self-defense mechanism was triggered, and Homer1, as a protective molecule, may increase to a certain extent, slowing the degree of damage." (PMID 38091015, 2024). "Overexpression of Homer1 could inhibit ER stress-related TXNIP/NLRP3-mediated pyroptosis by regulating the AMPK signaling pathway, which in turn improved the visual function of the retina after ischemia." (PMID 38069134, 2023).
neuroblastoma (3 papers, 2009 to 2025). Neuroblastoma (NB) is the most common solid, extracranial childhood tumor. "Specific Homer1 knockdown was confirmed by western blot analysis of extracts from a human neuroblastoma cell line (B-35) treated with the same morpholinos for 12 or 24 hours." (PMID 19650914, 2009).
Parkinson disease (3 papers, 2015 to 2020). A progressive degenerative disorder of the central nervous system characterized by loss of dopamine producing neurons in the substantia nigra and the presence of Lewy bodies in the substantia nigra and locus coeruleus. "Homer1, a postsynaptic scaffolding protein regulating intracellular calcium mobilization, has been reported to play a role in both glutamate-mediated excitotoxicity and neuronal injury in in vitro Parkinson’s disease model." (PMID 30237514, 2018). "Also, in Parkinson’s disease model or glutamate treatment, inhibition of ER Ca2+ release through Homer1 knockdown reserves mitochondrial function and reduces apoptosis." (PMID 30237514, 2018).
retinal ischemia (3 papers, 2021 to 2023). A ischemic disease that involves the retina. "With the development of the pyroptosis, Homer1 co-localized with RGCs and peaked 24 h after retinal ischemia." (PMID 38069134, 2023). "The hematoxylin and eosin (HE) staining of retinal cross-sections showed the decreased thickness of retinal tissue 24 h after retinal ischemia, and this effect was markedly inhibited with Homer1-OE treatment, while Homer1-KD further exacerbated tissue damage." (PMID 38069134, 2023). "Immunofluorescence showed that the proportion of pyroptosis cells in Homer1-OE was lower than that of the retinal ischemia (I) group." (PMID 38069134, 2023). "Although it was found in this study that Homer1 can regulate ER stress-related TXNIP/NLRP3-mediated pyroptosis through the AMPK signaling pathway in the MCAO–retinal ischemia model, some limitations cannot be ignored." (PMID 38069134, 2023). "However, little is known about pyroptosis following middle cerebral artery occlusion (MCAO)-induced retinal ischemia and the regulatory mechanisms involved by Homer1 for the development of pyroptosis." (PMID 38069134, 2023). "In conclusion, it was suggested that Homer1 may protect against MCAO-induced retinal ischemia and RGCs pyroptosis by inhibiting endoplasmic reticulum stress-associated TXNIP/NLRP3 inflammasome activation after MCAO-induced retinal ischemia." (PMID 38069134, 2023). "Therefore, further studies are needed to be carried out to investigate other mechanisms of action of Homer1 in retinal ischemia." (PMID 38069134, 2023). "Notably, the occurrence of pyroptosis coincided with the change of Homer1 expression in the retina after retinal ischemia and Homer1 also co-localized with RGCs." (PMID 38069134, 2023). "First, Homer1 could exert protective effects against retinal ischemia in a variety of ways." (PMID 38069134, 2023). "In our study, Bip and CHOP proteins as markers of ER stress changed accordingly with the regulation of Homer1 in this experiment, verifying the role of ER stress in the TXNIP/NLRP3-mediated pyroptosis-signaling pathway after MCAO-induced retinal ischemia." (PMID 38069134, 2023). "It was demonstrated that overexpression of Homer1 not only alleviated RGCs pyroptosis and inhibited the release of pro-inflammatory factors but also led to the increase in phosphorylation of AMPK, inhibition of ER stress, and preservation of visual function after retinal ischemia." (PMID 38069134, 2023).
Stroke (3 papers, 2019 to 2021). Sudden impairment of blood flow to a part of the brain due to occlusion or rupture of an artery to the brain. "We then performed high-resolution confocal microscopy to analyze glial cell-mediated engulfment of the presynaptic protein SYP and the postsynaptic protein Homer-1 in the gliosis region at 14 days after stroke." (PMID 34836962, 2021).
cocaine addiction (2 papers, 2017 to 2024). "A prior study examined the association between genetic variants of HOMER1 and HOMER2, located on chromosomes 5q14.2 and 15q24.3, respectively, with cocaine dependence." (PMID 39518903, 2024). "This study reported a significant link between the HOMER1 SNP rs6871510 genotypes and cocaine dependence." (PMID 39518903, 2024).
Coronary Artery Disease (2 papers, 2014 to 2022). "Spearman correlation analysis was used to analyze the correlation between serum Homer1, SAH, Hcy, FGF23 levels and Gensini score, and multivariate unconditional Logistic regression was used to analyze the risk factors of coronary heart disease." (PMID 35546659, 2022).
dementia (2 papers, 2023 to 2025). Loss of intellectual abilities interfering with an individual's social and occupational functions. "CircHOMER1, which is produced by the HOMER1 gene, is highly intriguing because the HOMER1 protein links neural channels and receptors that the Aβ protein in the AD brain, and circHOMER1, was found to be significantly associated with AD diagnosis, clinical neurological staging, and dementia severity." (PMID 40453757, 2025). "Importantly, five of these pre-mRNAs (DOCK1, HOMER1, MAN2A1, RTN4, and ST18) were also found to correlate with dementia severity in the parietal cortex, suggesting that these circRNAs in general correlate with AD progression." (PMID 37266374, 2023).
epilepsy (2 papers, 2012 to 2023). A brain disorder characterized by episodes of abnormally increased neuronal discharge resulting in transient episodes of sensory or motor neurological dysfunction, or psychic dysfunction. "Based on the DEGs analysis, we further determined the vital role of Homer1, a key component of the PSD associated with the etiology of epilepsy and related to VPA efficacy, in the glutamate‐induced HT22 cell line." (PMID 36353757, 2023).
glioblastoma (2 papers, 2023 to 2025). The most malignant astrocytic tumor (WHO grade IV). "In these samples, MAP2 marks neurons, synapsin-1 marks presynaptic puncta, Homer-1 marks postsynaptic puncta, and SB28 glioblastoma cells are inherently labeled by GFP." (PMID 40404658, 2025).
Huntington disease (2 papers, 2022 to 2025). Huntington disease (HD) is a rare neurodegenerative disorder of the central nervous system characterized by unwanted choreatic movements, behavioral and psychiatric disturbances and dementia. "In a Huntington’s disease (HD) mouse model, treatment with memantine or targeting the NMDAR/TRPM4 complex with FP802 restored gene expression, notably Inhba, Homer1 and Bdnf, and attenuated the decrease of the HD disease marker Ppp1r1b (DARPP-32)." (PMID 41339520, 2025). "Furthermore, we found that some DORCs, such as CNR1, HOMER1, ADORA2A, and DRD2, have been reported to be downregulated in patients with Huntington's disease in the striatum." (PMID 38091510, 2022).
ischemic stroke (2 papers, 2021 to 2024). A stroke disorder caused by obstruction of blood flow to the brain, due to thrombotic (local blood clot formation) or embolic (due to a blood clot or other material traveling from another site) event. "In the early stages of ischemic stroke, the expression of Homer1 in the ischemic penumbra cortex was highest at 8 h and was mainly expressed in neurons." (PMID 38091015, 2024). "Given that necroptosis is accompanied by neuroinflammation, which plays a crucial role in ischemic stroke, we investigated the effects of Homer1-KD on pMCAO-induced neuroinflammation." (PMID 38091015, 2024). "Homer1 ameliorates ischemic stroke by inhibiting necroptosis-induced neuronal damage and neuroinflammation." (PMID 38091015, 2024). "However, the current study remains limited, and further studies are needed to reveal the translational potential of Homer1 in patients with ischemic stroke." (PMID 38091015, 2024). "Homer1 ameliorates brain injury induced by ischemic stroke in conditional knockout mice." (PMID 38091015, 2024). "Therefore, we conclude that Homer1 can ameliorate the prognosis of ischemic stroke by reducing necroptosis-induced brain injury and neuroinflammation." (PMID 38091015, 2024). "However, the relationship between Homer1 and proinflammatory necroptosis in ischemic stroke remains unclear." (PMID 38091015, 2024). "We found that 14 days after ischemic stroke, MEGF10KO or MERTKKO in microglia/macrophages or astrocytes resulted in reduced engulfment of SYP+ and Homer-1+ synaptic puncta in microglia/macrophage or astrocytes compared with controls." (PMID 34836962, 2021). "We found that 14 days after ischemic stroke, astrocytes and microglia/macrophages engulfed synaptic elements immunolabeled for both presynaptic (synaptophysin, SYP) and postsynaptic (Homer-1) proteins in the microgliosis and astrogliosis areas." (PMID 34836962, 2021).
mood disorder (2 papers, 2017 to 2022). A cognitive disorder a disturbance in which the person's mood is hypothesized to be the main underlying feature. "Genome-wide association studies (GWAS) have shown that Homer1 is a key target for mood disorders and antidepressants." (PMID 35610650, 2022). "GWAS have revealed that Homer1 plays an important role mood disorders as well as antidepressant treatments." (PMID 35610650, 2022).
osteosarcoma (2 papers, 2021 to 2025). A usually aggressive malignant bone-forming mesenchymal neoplasm, predominantly affecting adolescents and young adults. "In preliminary analyses we also found that a correlation existed between the native protein levels of CaSR and Homer1 in the commonly used osteosarcoma cell lines MG63 (ATCC® CRL-1427TM) and SAOS-2 (ATCC® HTB-85TM)." (PMID 34204449, 2021). "In MG63 osteosarcoma cells, CaSR and HOMER1 co-regulate AKT Ser473 and GSK3β-S9 phosphorylation." (PMID 40059879, 2025). "Both osteosarcoma cell lines exhibited markedly enhanced Homer1 expression compared to primary osteoblasts, along with increased expression of CaSR, mTOR, the mTORC2 specific protein Rictor, but not the mTORC1 specific Raptor, and the effects were particularly pronounced in SAOS-2." (PMID 34204449, 2021). "The involvement of CaSR and Homer1 in AKT Ser 473 and GSK 3β-S9 phosphorylation has been demonstrated in MG 63 osteosarcoma cells." (PMID 40059879, 2025). "Whether increased CaSR/Homer1 expression and resultant AKT activation contributes to the high survival, high growth phenotype of osteosarcoma cells and are thus potential targets for the chemotherapy of osteosarcoma, remains to be determined." (PMID 34204449, 2021).
prostate carcinoma (2 papers, 2024 to 2025). A carcinoma that arises from epithelial cells of the prostate gland. "A subset of bone marrow samples that displayed a high frequency of CTC-IGC from the prostate cancer patient cohort were stained with HOMER1, TNFRSF9, and LRP1." (PMID 39483900, 2024). "In publicly available data for previously treated patients, high expression of TNFRSF9 and LRP1 significantly correlated with a shorter progression free survival in patients with prostate cancer; HOMER1 was not statistically significant (p-value = 0.183)." (PMID 39483900, 2024).
African trypanosomiasis (1 paper, 2025). "KEGG pathway enrichment analysis of these shared genes (corrected p < 0.05) revealed significant overrepresentation in glutamatergic synapse (encompassing HOMER1, HOMER2, PLCB4, and ADCY9) and African trypanosomiasis (containing SELE, MYD88, and PLCB4)." (PMID 41153960, 2025).
alcohol use disorder (1 paper, 2024). "While there are limited data on HOMER1 expression in alcohol use disorder (AUD), most findings focus on HOMER2." (PMID 39518903, 2024).
amnesia (1 paper, 2020). Pathologic partial or complete loss of the ability to recall past experiences ( AMNESIA, RETROGRADE) or to form new memories ( AMNESIA, ANTEROGRADE). "Therefore, the promoted gene and protein expression of Arc, Egr1, Homer1 and Narp by EA treatment also indicated the therapeutic effect of EA on scopolamine-induced amnesia." (PMID 33183243, 2020).